COL1A2 (collagen type I alpha 2 chain)
Diseases named in the same sentence as COL1A2 in open-access papers (continued):
Sharing a sentence is not in itself a finding about the gene and the disease.
tumor (continued). "Col1a1, Col1a2, Col2a1, Col3a1, and Col5a2, which were commonly found in normal ECM of mouse, pig, and human breast tissues, were also identified in tumor ECM in addition to Col4a2, Col5a1, Col6a1, Col6a2, Col6a3, and Col7a1." (PMID 36547361, 2022). "Among the interactions involved in tumor invasion and growth, extracellular matrix interaction scores were higher between tumor stroma and post-treatment tumor (tumor stroma ligand: COL1A1, COL1A2, and COL3A1; post-treatment tumor receptor: ITGA2)." (PMID 36505794, 2022). "Firstly, tumor cells secrete Tsp2 to induce the transformation of normal fibroblasts to TAFs, and TAFs remodel the extracellular matrix by secreting COL1A1, COL1A2, COL5A1, FN1, and VCAN." (PMID 35982904, 2022). "From the analysis of the most relevant m/z features for the classification, as calculated by forward feature extraction, we can conclude that COL1A1, COL1A2, and COL3A1 play a central role in tumor progression." (PMID 35956764, 2022). "The scRNA-seq data showed that ITGA2 was mainly expressed in tumor cells, while its ligands COL1A1, COL1A2, COL8A1, FN1, and HSPG2 were expressed in fibroblasts and endothelial cells." (PMID 35719923, 2022). "The patients with high KDR, PDGFRA, LRP1, COL1A2, and SAMD9 expression had shorter OS (log-rank test, P < 0.05), indicating that tumor antigens were critical for the progression of diffuse gliomas." (PMID 34815785, 2021). "We found that COL1A2, COL3A1, COL5A2, tumor mediators targeting of relevant structural components of the extracellular matrix (ECM) were activated to drive CAFs to synthetize fibrillar collagen creating an aberrant microenvironment." (PMID 34458147, 2021). "COL1A1 and COL1A2 are two members of Type I collagen, interestingly, both of COL1A1 and COL1A2 are dysregulated in several cancers and involved in tumor invasion and progression." (PMID 34399848, 2021). "When investigating the mRNA expression of COL1A2, POSTN, GREM1, MMP1, and MMP9 in patient material, we found all five genes to be upregulated in HNSCC tumor tissue compared to normal oral tissue." (PMID 34283070, 2021). "In summary, we identified COL1A2 and its similar genes as the potential biomarkers for assessing the infiltration levels of immune cells using a comprehensive analysis of bioinformatics, which could help us better understand the mechanism of tumor immune cell infiltration in ESCA." (PMID 33543230, 2021). "COL3A1, COL1A2, COL15A1, ASPN, and MXRA5 were higher expressed in tumor samples, while OGN was lower expressed." (PMID 32300359, 2020). "Among these genes, COL1A1, COL1A2, FN1 and COL5A2 were considered as perspective effective targets that play prominent roles in the development and recurrence of the tumor, including STAD." (PMID 33193601, 2020). "The collagen family (COL1A2, COL1A1, COL6A3, and COL5A1), DCN, FBLN1, and POSTN were the most abundant components of the tumor ECM." (PMID 33613617, 2020). "Principal component analysis and random forest analysis were employed to further screen for six hub genes, including ISLR, COL1A2, CDH11, SPARC, COL3A1, and COL1A1, which exhibited a good ability to differentiate between tumor and normal samples." (PMID 32612640, 2020). "Stromal DKK3 expression in human tumours positively correlated with the expression of CAF markers ACTA2, FAP and COL1A2, supporting a link between DKK3 and CAFs." (PMID 30631061, 2019). "The results of qPCR experiment performed in HNSCC tissues suggested that APP and COL1A2 were significantly upregulated in HNSCC tissues when compared to adjacent matched tissues, implying the potential tumor promoter role of them in HNSCC progression." (PMID 31304688, 2019). "Highly interrelated nodes, such as COL1A1, COL1A2, POSTN, ADAMTS4, and CD34, have been reported to regulate the tumor microenvironment and promote the growth, angiogenesis, and invasion of malignancies." (PMID 31480381, 2019).
tumor (continued). "Gene ontology analysis of these DEGs showed that in advanced stage tumours, pathways such as cell adhesion (VCAN), ECM receptor interaction (COL1A2, COL3A1, ITGA11, and TNN) and pathways in cancer (JUN, and MYC) getting deregulated." (PMID 31292488, 2019). "Changes in several ECM components known to promote growth of tumour cells, such as the collagens COL1A1, COL1A2, and the MMP2 metalloprotease were also evident in XRCC1 KD cells, again reflecting an activated fibroblast phenotype." (PMID 29568385, 2018). "We first validated expression of COL1A1, COL1A2, and COL3A1, in OSCC fibroblast pairs isolated from tumor or its adjacent stroma, as well as in two OSCC tumor cell lines, CAL27 and HSC-3, using quantitative PCR." (PMID 27128408, 2016). "The methylation statuses of the promoters of 11 tumor-related genes (p16, RASSF1A, E-cadherin, H-cadherin, MGMT, DAPK, DCC, COL1A2, TAC1, SST, and GALR1) were analyzed in 133 HNSCC cases using quantitative methylation-specific PCR." (PMID 27027429, 2016). "Whole tumour and parenchymal samples demonstrated differential gene expression, with 289 genes significantly overexpressed in the whole tumour, many of which were consistent with stromal gene expression (e.g., COL6A3, COL1A2, POSTN, TIMP2)." (PMID 19401702, 2009). "Additionally, azvudine regulated the interactions from other tumor immune cells to CD4+ T and CD8+ T cells through ligand‒receptor pairs such as COL1A2‒(ITGA1 + ITGB1), CCL4‒CCR5, CCL6‒CCR2, and CXCL16‒CXCR6." (PMID 39819859, 2025). "Between ARGs_High tumour cells and T cells, ITGB2-ICAM1 and TGFB1-TGFBR1 were ligand-receptor pairs with strong regulatory potential, while EDN1, JUNB, SOCS3, VIM and COL1A2 were top genes target to TGFB1." (PMID 40830065, 2025). "COL1A2 (collagen type I alpha 3 chain) is a key structural component of the ECM and may indicate its role in tumor progression and TME." (PMID 40362431, 2025). "Given the pivotal role of COL1A2 in shaping the composition and organization of the ECM, elucidating how these ECM alterations are translated into intracellular signaling pathways that drive tumour cell behaviour is also critical." (PMID 41561769, 2025). "However, other HGs, especially collagen‐related genes, including COL1A1, COL1A2, ITGA2, and POSTN revealed slightly higher methylation in tumor tissue than in normal tissue." (PMID 38639039, 2024). "Strikingly, examining the source of collagen gene expression (COL1A1, COL1A2, COL3A1, COL6A1, COL8A1, COL10A1) provided clarity that the majority of genes expressed in the tumor samples represent transcripts of the MSC-related component of the tissue microenvironment." (PMID 36940196, 2023). "In the context of tumor progression, COL1A2 overexpression drives immune suppression and contributes to tumor immune escape for COAD, indicating that targeting COL1A2 might be a novel strategy to improve the immunotherapy efficacy of COAD." (PMID 37805556, 2023). "Furthermore, we also evaluated the expression of myofibroblast marker genes, such as COL1A2, COL3A1, ACTA2, and FAP, in the tumor microenvironment using an IHC assay." (PMID 37953225, 2023). "While the hypoxic tumor microenvironment generates abnormal new blood vessels through both tumor-induced and CAF-induced factors, it also is a necessary factor for the conversion of NFs to CAFs, mediated through HIF1α-induced NFκB, CCL5, COL1A2, and αSMA." (PMID 37046676, 2023). "Furthermore, MDSCs contributed to ECM remodeling and vascular‐related gene expression in a subset of recurrent tumor CAFs, including ACTA2, TMP1, MMP2, and COL1A2." (PMID 37743226, 2023). "Moreover, PECAM1+ cells (ECs) in cluster 8 ECS (COL1A1, COL1A2, COL3A1, PDGFRB, and ACTA2) showed an endothelial-mesenchymal transformation phenotype, which contributed to tumor progression." (PMID 37533434, 2023).
tumor (continued). "Overall, these data together showed that COL1A1, COL1A2, and COL6A3 are the key molecules that might regulate the tumor pEMT phonotype by interacting with SDC1 and accelerate the malignant progression of cancer patients." (PMID 38002057, 2023). "Gene expression of COL1A1, COL1A2, COL6A3, FN1, and THY1 in CAFs as well as COL4A1 and COL4A2 in Angiogenic_EC had a highly significantly positive correlation with the proportion of malignant tumor cells." (PMID 38002057, 2023). "Both populations displayed striking transcriptional divergence following chemotherapy exposure with 906 and 817 DEGs within the COL1A2 and IER2 populations respectively, whilst the MFAP5 fibroblasts showed highest transcriptional difference in tumor vs normal comparisons." (PMID 36253784, 2022). "Importantly, the expression of COL1A2, LOX and LTBP2 significantly correlated with high tumor stage, with LOX and LTBP2 further impacting patient overall survival." (PMID 35340765, 2022). "On the other hand, COL1A2, COL3A1, COL5A1, FN1, and SPARC may be more involved in tumor progression from stage 1 to stage 2, at which the tumor cells gain the ability to invade surrounding tissues." (PMID 35739492, 2022). "Notably, in Kitata and colleagues dataset, the protein abundance of COL1A2 and COL14A1 was similar between tumor and normal tissues, while the abundance of the Hyp sites on each of those proteins were well above or below the 95% confidence interval." (PMID 36026437, 2022). "Besides, we found three genes, including COL1A1, COL3A1, and COL1A2, were significantly upregulated in TCGA BRCA tumor samples compared with normal controls, whereas the other seven genes were not significantly changed in BCa tumor samples (data now shown)." (PMID 35274048, 2022). "Gene expression analysis of paired tumor-non-tumor samples from TCGA-LIHC cohort (n = 438) also showed 1.13-(p < 0.001), 1.01-(p < 0.01), and 1.07-(p < 0.001) fold reduction in COL1A1, COL1A2 and COL4A1 mRNA expression in the HCC tumor compared to the non-tumor ‘normal’ liver samples." (PMID 31181620, 2019). "Among them, 13 proteins correlated with clinicopathological parameters and of these proteins, eight proteins were identified in neoplastic islands (ACTR2, CSTB, COL1A2, LTA4H, PGK1, NDRG1, S100A8, S100A9) and five proteins were identified in tumor stroma (COL6A1, FSCN1, ITGAV, MB, THBS2)." (PMID 30185791, 2018). "The majority of proteins (ACTR2, CSTB, LTA4H, PGK1, NDRG1, FSCN1, ITGAV, THBS2) significantly associated with clinical parameters showed lower expression in the ITF of the tumor stroma or neoplastic islands, with the exception of COL6A1, COL1A2, S100A8, S110A9, and MB." (PMID 30185791, 2018). "Common up-regulation of genes such as COL1A1, COL1A2, PGF, LRRFIP1, TMEFF2 or TGFB1 suggested an important role of this pool of cells in blood vessel formation, angiogenesis, permeability and proliferation pathways, essentials functions in tumour progression." (PMID 20735813, 2010). "Up-regulated genes such as COL1A1, COL1A2, PGF or TGFB1, suggested an important role of these compartment in blood vessel formation, angiogenesis, permeability and invasiveness, essential functions in tumour progression." (PMID 20735813, 2010). "The spatial localization of HYP peptides for COL1A1, COL1A2, COL5A1 and COL3A1 exhibited distinct region-specific patterns in dormant D-HEp3 compared to awakened P4HA2-depleted D-HEp3 cells, suggesting differential regulation of collagen hydroxylation across tumor zones." (PMID 40671813, 2025). "Corresponding m/z from collagen type I alpha 2 (COL1A2), cathepsin (CTSG), elongation factor 1-alpha 1 (EEF1A1), EH domain-containing protein 2 (EHD2), epiplakin 1 (EPPK1), prelamin-A/C (LMNA), and prolargin (PRELP) showed higher intensity distribution in HND in comparison to LND tumour areas." (PMID 40603632, 2024).
tumor (continued). "The current study shows that COL1A2, followed by TIMP-1, are the most potent CAF-markers found and verified at the transcriptome and protein level across multiple CAF types, differentiating CAF from tumour epithelia and normal fibroblast in HNSC patient samples." (PMID 37626157, 2023). "The results suggested that tumor immune infiltration and tumor immune escape might be involved in COL1A2-medidated cancer development, providing clues for improving the immunotherapy efficacy of COAD by targeting COL1A2." (PMID 37805556, 2023). "We detected 24 genes across the tumor tROIs that showed a high CV (i.e., were among the genes with the top 20% highest CV in seven out of seven cases), such as multiple collagens (COL1A1, COL1A2, COL3A1, COL5A1, COL5A2), S100A8, S100A9, FN1, or Early growth response protein 1 (EGR1)." (PMID 37511126, 2023). "Furthermore, the gene expression levels of COL1A1 with SDC1, COL1A2 with SDC1, and COL6A3 with SDC1 were significantly positively correlated in TCGA-BC and TCGA-PDAC, supporting their potential interaction in the surrounding tumor niche." (PMID 38002057, 2023). "COL1A2 expression did not correlate significantly with the tumour stage, lymph node, unknown metastasis and tumour grade." (PMID 33889206, 2021). "In addition, KC7F2 also could attenuate the effect of TGF‐β1 and tumour cell CM on the expression of α‐SMA and COL1A2." (PMID 33943003, 2021). "Consequently, dysregulated ECM remodeling orchestrated by COL1A2 may modulate FAK activation, establishing a mechanistic axis that links extracellular matrix dynamics to intracellular signaling cascades fundamental to tumour progression." (PMID 41561769, 2025). "Genes that encoded extracellular matrix (ECM) components, such as COL1A1, COL1A2, LUM and FN1, were specifically expressed by fibroblasts, suggesting that the ECM in the NPC microenvironment was highly complex and might interact with surrounding tumor and stromal cells via integrin signaling." (PMID 33750785, 2021). "And transcriptional data reveal that compared to the adjacent non-tumorous samples, expression of COL3A1, COL1A2, FBN1, IGFBP7, and FSTL1 was significantly elevated in the tumor tissue." (PMID 38478111, 2024). "The results showed that the expression levels of ITGA2, ITGB6, LAMA3, LAMB3, and LAMC2 are significantly correlated with the tumor stage of PAAD patients, while the expression levels of COL1A2 are not correlated with the tumor stage of PAAD patients." (PMID 35899199, 2022). "Two fibroblast subpopulations, characterized by high level expression of COL1A2 and IER2, were markedly increased within the tumor microenvironment and almost completely absent in adjacent normal esophageal tissue." (PMID 36253784, 2022). "Results demonstrate that tumor scaffold, in the absence of LKB1 overexpression, repressed COL1A2 and IGFBP4, and enhanced COL4A1 compared to MDA-MB-231 cells grown on TCP." (PMID 35755802, 2022). "Analysis of gene expression by quantitative real-time RT-PCR in indirectly co-cultured CCD-1068SK fibroblasts revealed that tumour cells did not influence the expression of COL1A1, COL1A2, CCN2 or Smad7 when compared to fibroblast monocultures." (PMID 24090133, 2013). "Indeed, as examples, the high expressions of fibroblasts, myofibroblast markers (COL1A1, COL1A2), and B cell markers (IGLC3, IGHG3) were found in our LMD-isolated stroma samples and TCGA tumor samples, but not in our LMD-isolated tumor parts." (PMID 33916417, 2021). "The expression of GREM1 and COL1A2 could not be detected in LK0824, LK0858, or LK0923 tumor monocultures by qRT-PCR; thus, the Ct-values were set to 40 in order to enable fold-change calculations using the comparative Ct method." (PMID 34283070, 2021).
cancer (163 papers, 2006 to 2025). A tumor composed of atypical neoplastic, often pleomorphic cells that invade other tissues. "Central to this axis, matrix cancer-associated fibroblasts secrete COL1A2 to mediate pathogenic ECM remodeling." (PMID 41561769, 2025). "COL1A2 displayed a positive association with M1 and M2 macrophages and cancer-associated fibroblasts." (PMID 38610959, 2024). "The miR-29 family negatively regulates collagen expression by directly targeting COL1A1’s and COL1A2’s mRNA transcripts, while the other miRNAs are linked to fibrosis and cancers, suggesting their effect on the synthesis of the ECM." (PMID 37895885, 2023). "Previous studies suggested that COL1A2 expression was up-regulated in multiple human carcinomas and abnormal increasing expression of COL12A1 was associated with a poor prognosis." (PMID 36776317, 2023). "Collagen I alpha 2 (COL1A2) is involved in carcinogenesis and modified expression of COL1A2 has been reported in association with several cancers." (PMID 33889206, 2021). "There is evidence of the involvement of members of the collagen family in carcinogenesis in several tissue types, and aberrant expression of COL1A1 and COL1A2 has been implicated in some cancers." (PMID 31181620, 2019). "Taken together, this suggests that COL1A2 is a gene for which methylation is more generally associated with tumorigenesis across different cancer types." (PMID 22028813, 2011). "Crucially, the compartmentalized expression of COL1A2 in matrix cancer-associated fibroblasts and PTK2/FAK activation in epithelial cells undergoing epithelial–mesenchymal transition suggests a paracrine signaling paradigm that transcends traditional cell-autonomous frameworks." (PMID 41561769, 2025). "Additionally, collagen degradation products, particularly those involving COL1A1 and COL1A2, can influence the epithelial-mesenchymal transition, a process associated with increased migratory and invasive capabilities of cancer cells." (PMID 40216311, 2025). "Our analysis focused on the interaction dynamics between COL1A2/ECM-high matrix cancer-associated fibroblasts (matrixCAFs) and PTK2 (FAK)-high Epithelial_EMT cells, hypothesized as critical mediators driving the transition from NMIBC to MIBC." (PMID 41561769, 2025). "Cancer-associated fibroblasts (78 cells; cluster 13) specifically expressed COL1A2, DCN, and LUM." (PMID 40102789, 2025). "In more detail, we found collagen (COL) 1A1 and COL1A2 as one of the most significant up-regulated genes in BM which is in line with previous studies reporting COL1A1 and COL1A2 to be associated with an aggressive and pro-metastatic phenotype in diverse cancer types." (PMID 36361816, 2022). "The COL1A2 gene mutation in pan-cancer was evaluated through the COSMIC database." (PMID 36057263, 2022). "COL1A2 encodes a type I collagen, one of main extracellular matrix proteins, which is controlled by its degrading matrix metalloproteinases (MMPs) and implicated in cancer development and progression." (PMID 33428680, 2021). "While aberrant expression of COL1A1 and COL1A2 is implicated in numerous cancers, the differential role of COL1A1 in malignant, premalignant and normal tissues remains unclear, and its clinical significance in HCC has not been elucidated." (PMID 31181620, 2019). "In cancer zone A, cancer cells primarily engaged in Col1a1/Col1a2-Itga9/Itgb and Fn1-Cd44 interactions to promote invasion and drive ECM remodeling." (PMID 40723284, 2025). "In cancer cells, methylation of the first exon of COL1A2, which is located at the regulator of the X-box (RFX) locus (at −1 to +20), is associated with increased RFX1 binding and decreased collagen transcription." (PMID 41425715, 2025). "Typically, fibroblasts produce heterotrimeric α1/α2/α1 collagen I, but, in contrast, cancer cells often lose the Col1a2 gene and start producing homotrimeric α1/α1/α1 degenerated collagen." (PMID 40427098, 2025).